IL37 (interleukin 37)
Diseases named in the same sentence as IL37 in open-access papers (continued):
Sharing a sentence is not in itself a finding about the gene and the disease.
diabetes (14 papers, 2017 to 2024). "We determined the diagnostic ability of IL-37 cut-offs to identify diabetes-related complications or patient subgroups by using Receiver Operating Characteristic analysis (c-statistics)." (PMID 36834391, 2023). "The results revealed that the low IL-37, diabetes mellitus, high CRP, NT-pro BNP, and hs-cTnI were independent risk markers for poor prognosis." (PMID 34580597, 2021). "The low IL-37, diabetes mellitus, high CRP, NT-pro BNP, and hs-cTnI were independent risk factors affecting poor prognosis of patients with ACS." (PMID 34580597, 2021). "Opportunistic fungal infections, such as the black fungus commonly seen in diabetics, hyperglycemia, COVID-19 patients, and linked to corticosteroids have all in common a dysregulated immune response that partly could also be attributed to IL-37." (PMID 35095801, 2021). "A link between IL‐37 and a dysregulated immune response in COVID‐19 and diabetes has also recently been proposed." (PMID 36757903, 2023). "Multinomial logistic regression analysis of IL‐37 and IL‐39 in type 2 diabetes mellitus (controls were the reference category)." (PMID 36757903, 2023). "Another study examined IL‐37 expression in kidney cells (podocytes) of T2DM patients with diabetic nephropathy, an important complication associated with diabetes." (PMID 36757903, 2023). "IL‐37 and IL‐39 levels (median and interquartile range) stratified by characteristics of type 2 diabetes mellitus patients." (PMID 36757903, 2023). "The low IL-37, diabetes mellitus, high CRP, NT-pro BNP, and hs-cTnI in the blood were included in the analysis, and the occurrence of cardiovascular events was taken as the dependent variable." (PMID 34580597, 2021). "Logistic regression revealed that low IL-37, diabetes, high CRP, NT-pro BNP, and hs-cTnI in the blood were independent risk factors for poor prognosis in patients with ACS." (PMID 34580597, 2021). "A great number of studies demonstrated that IL-37 is involved in the occurrence and development of chronic inflammation and autoimmune diseases such as rheumatoid arthritis, systemic lupus erythematosus, and diabetes." (PMID 28781417, 2017). "Black fungus, diabetes, corticosteroids, and coronavirus disease 2019 (COVID-19) all have a dysregulated immune response in common, which partly could also be attributed to interleukin 37 (IL-37)." (PMID 35095801, 2021). "This indicated that if the patients' IL-37, CRP, NT-pro BNP, hs-cTnI, and diabetes can be well controlled, the prognosis of patients can also be improved." (PMID 34580597, 2021). "In this study, we observed a paradoxical increase in circulating levels of IL-37 among patients with diabetes and DCM, which may indicate a compensatory response to IL-37 resistance in these pathological conditions." (PMID 38790051, 2024). "However, plasma IL-37 level in CHF patients with DM was significantly higher compared to that in patients without diabetes (P < 0.01)." (PMID 28781417, 2017).
multiple sclerosis (14 papers, 2017 to 2024). A progressive autoimmune disorder affecting the central nervous system resulting in demyelination. "Higher IL37 levels were associated with younger age (p = 0.047) and lower Multiple Sclerosis Severity Score (MSSS; p = 0.039)." (PMID 31861585, 2019). "Iranian scholars found that the serum IL-37 concentration in patients with multiple sclerosis and optic neuromyelitis increased, suggesting that IL-37 is involved in its pathophysiological mechanism." (PMID 33381572, 2020). "There are also animal experiments that show that the secretions of human periodontal ligament cells pretreated with hypoxia can have anti-inflammatory effects through IL-37 in multiple sclerosis experimental models." (PMID 33381572, 2020). "Also, the prognostic value of IL-37 has been demonstrated for several diseases, including epithelial ovarian cancer, gastric cancer, multiple sclerosis, spinal cord injury, acute ischemic stroke, and heart failure." (PMID 34367169, 2021). "A recent report reveals that IL-37 is reduced in blood leukocytes of multiple sclerosis (MS) 22, suggesting that this anti-inflammatory pathway might be defective in MS." (PMID 33391457, 2021). "Interestingly, studies have pointed out that IL-37 is involved in the pathogenesis of multiple sclerosis, a neurological disease." (PMID 33381572, 2020). "Thus, the goals of the present study were to evaluate the therapeutic effects of IL-37 in a mouse model of multiple sclerosis, and if so, whether this is mediated via the extracellular receptor complex IL-1R5/IL-1R8." (PMID 33391457, 2021). "However, whether IL-37 exerts beneficial actions in neuroinflammatory diseases, such as multiple sclerosis, remains to be elucidated." (PMID 33391457, 2021). "In addition, two recent studies focusing on the central and peripheral nervous systems have demonstrated the therapeutic potential of IL-37 in autism spectrum disorders (ASD) and multiple sclerosis (MS)." (PMID 36040311, 2022).
atopic dermatitis (13 papers, 2015 to 2025). "Consequently, IL-37 is linked to IL-18, which plays a role in the pathogenesis of atopic dermatitis (AD), consistent with our studies." (PMID 38067193, 2023). "For atopic dermatitis, transcriptomic analysis has shown a low expression of IL‐37 in lesions compared with non‐lesional skin; however, we failed to observe this in epidermal protein samples." (PMID 39157924, 2025). "This review summarizes and analyzes the accumulated experimental data on the role of IL-37 in the pathogenesis of AD, such as allergic rhinitis, bronchial asthma, and atopic dermatitis." (PMID 31993235, 2019). "In addition, IL-37 also plays a role in maintaining homeostasis between host immune responses and microbial species; however, its role in the skin microbiome in atopic dermatitis (AD) has not been thoroughly studied yet." (PMID 38067193, 2023).
Crohn disease (13 papers, 2014 to 2026). A gastrointestinal disorder characterized by chronic inflammation involving all layers of the intestinal wall, noncaseating granulomas affecting the intestinal wall and regional lymph nodes, and transmural fibrosis. "IL-37 increases in response to inflammatory stimulation, probably acting as a self-regulator of the defensive inflammatory reaction, and its presence has been observed in several inflammatory disease conditions (for example in the mucosa of patients with Crohn’s disease)." (PMID 24884937, 2014). "T-cell subsets from healthy control (HC), Crohn's disease (CD) and ulcerative colitis (UC) peripheral blood mononuclear cells (PBMC) and lamina propria mononuclear cells (LPMC) were assessed for expression of IL-37 and its receptors by flow cytometry." (PMID 41683959, 2026).
endometriosis (13 papers, 2018 to 2025). The growth of functional endometrial tissue in anatomic sites outside the uterine body. "Cytokines such as IL-37, IL-17A, IL-10, and IL-2 play essential roles in modulating immune responses in endometriosis." (PMID 39595927, 2024). "IL-37 is an anti-inflammatory cytokine found in the serum and peritoneal fluid of patients with endometriosis." (PMID 38337827, 2024). "Higher levels of serum IL-37 and IL-10, and significantly lower levels of serum IL-17A and IL-2 were detected in patients with endometriosis." (PMID 39595927, 2024). "Several studies have reported that levels of IL-37 are significantly elevated in the peripheral blood and peritoneal fluid of women with endometriosis." (PMID 39767772, 2024). "IL‐37 is another essential blood factor that indicates the presence of inflammation such as endometriosis, as we found in this study." (PMID 34557653, 2021). "Inflammation was assessed using the peritoneal concentration of TNF‐α and serum levels of IL‐37 as crucial inflammatory markers in endometriosis." (PMID 34557653, 2021). "Different with other members of IL-1 family, IL-37 has been proved to be an anti-inflammation cytokine in numerous inflammatory disorders, including endometriosis." (PMID 34429116, 2021). "Jiang and coworkers introduced IL‐37 as a biomarker for endometriosis diagnosis because they found the increased levels of this biomarker in human endometriotic cases." (PMID 34557653, 2021). "For endometriosis, serum IL-37 cut-off levels of 69.84 pg/mL, and 5.99 pg/ml, both with high sensitivity and specificity, have been reported." (PMID 34367169, 2021). "Previous studies have revealed that IL-37 can inhibit the release of matrix metalloproteinases (MMPs) in other diseases, such as endometriosis." (PMID 32733162, 2020). "IL-37 also has a capacity to affect the occurrence and development of endometriosis in a mouse model." (PMID 31507610, 2019). "IL-37 has been shown to correlate positively with disease severity in endometriosis where IL-37 mRNA correlated inversely to NF-κβ." (PMID 29641433, 2018). "IL37 gene polymorphisms have been studied in relation to other inflammatory conditions but not extensively in endometriosis." (PMID 39767772, 2024). "Here, in our present study, the data revealed that recombinant human IL-37 (rhIL-37) could inhibit the development of endometriosis through increasing the ratio of Th1/Th2 cells." (PMID 34429116, 2021). "The levels of IL‐37 in blood serum correlate with endometriosis severity." (PMID 34557653, 2021). "The findings of IBD may explain the changes in IL-37 and other inflammatory factors in endometriosis." (PMID 32145751, 2020). "The level of IL-37 reportedly correlates with the severity of endometriosis." (PMID 32145751, 2020). "Further studies suggest that a triple combination panel of Chi3l1/IL-37/CA125 and a quadruple combination panel of Chi3l1/CA125/endocan/copeptin can provide more sensitive and specific diagnoses of the endometriosis stage, especially moderate-to-severe endometriosis." (PMID 39769202, 2024). "One study showed that IL-37, an anti-inflammatory factor primarily produced by T-helper cells, acts as a trigger for pro-inflammatory factors such as IL-6, IL-8, and VEGF, thereby participating in the pathogenesis of endometriosis and enhancing angiogenesis." (PMID 38337827, 2024). "IL-37 synthesis is enhanced by IL-1β, TNF-α, IFN-γ, and TGF-β in endometriosis." (PMID 32145751, 2020). "However, the potential role of IL-37 in the pathogenesis of endometriosis has not been extensively investigated." (PMID 32145751, 2020).
pulmonary fibrosis (13 papers, 2018 to 2025). Chronic progressive interstitial lung disorder characterized by the replacement of the lung tissue by connective tissue, leading to progressive dyspnea, respiratory failure, or right heart failure. "In pulmonary fibrosis, IL-37 reduces collagen deposition and promotes autophagy, thereby counteracting interstitial fibrosis." (PMID 41293155, 2025). "As lung cell apoptosis is very important in lung fibrosis, they performed siRNA-mediated silencing of IL-37 in primary mouse AECs or A549 cells and found that IL-37 was protective against oxidative stress–induced AEC death." (PMID 37681924, 2023). "The protective effect of IL-37 has also been shown in other lung diseases such as idiopathic pulmonary fibrosis (IPF)." (PMID 36551790, 2022). "Similarly, a recent study found that patients with idiopathic pulmonary fibrosis (IPF) have reduced lung IL-37 expression." (PMID 41293155, 2025). "Besides, IL-37 was decreased in the model of idiopathic pulmonary fibrosis." (PMID 34025645, 2021). "In vivo animal study found IL-37 was decreased in the mice model with idiopathic pulmonary fibrosis (IPF) and IL-37 repressed TGF-β signaling in IPF fibroblasts." (PMID 34025645, 2021). "A previous study conducted by Kim MS further reported that IL-37, an anti-inflammatory cytokine, exhibits inhibitory effects on TGF-β1 signaling and enhances autophagy in IPF fibroblasts, ultimately improving the condition of IPF pulmonary fibrosis." (PMID 37789433, 2023).
Sepsis (13 papers, 2016 to 2026). Sepsis is defined as life-threatening organ dysfunction caused by a dysregulated host response to infection. "In recent years, the novel anti-inflammatory IL-35, IL-37, and IL-38 have also been implicated in sepsis immunosuppression, partly by inhibiting the release of pro-inflammatory mediators." (PMID 40364841, 2025). "The most prominent cytokines in sepsis related immunosuppressive were IL-4, IL-10, IL-27, IL-37, IL-38 and TGF-β." (PMID 40364841, 2025). "This upregulation of IL-37 is closely correlated with the severity of immunosuppression induced by sepsis." (PMID 39267971, 2024). "IL-37 represents a promising therapeutic target for pediatric sepsis." (PMID 41766906, 2026). "Additionally, immune mediators such as the immunosuppressive cytokine IL-37 contribute to the severity and extrapulmonary spread of S. pneumoniae to potentially induce sepsis and systemic complications." (PMID 38667530, 2024). "Similarly, it is reported that the upregulation of IL-37 in sepsis patients is of great significance as it has the potential to impede the proliferation and release of pro-inflammatory cytokines." (PMID 39267971, 2024). "Another study also demonstrated that IL-37 could significantly downregulate the expression of HLA-DR and CD86 in septic mice and inhibit antigen presentation, indicating that IL-37 has an immunosuppressive effect in sepsis." (PMID 36209190, 2022). "Sepsis-related anti-inflammatory cytokines mainly include IL-4, IL-10, and IL-37." (PMID 36209190, 2022). "Likewise, recent characterizations of IL-37 have shown it to possess potent anti-inflammatory properties in the context of sepsis." (PMID 34988552, 2021). "By reducing harmful ROS and promoting anti-inflammatory mechanisms, Retinoic acid and IL-37 may produce greater reductions in sepsis mortality if administered together versus if they were administered separately." (PMID 34988552, 2021). "The recently identified cytokines—interleukin (IL)-35 and interleukin (IL)-37—have been described for their anti-inflammatory and immune-modulating actions in numerous inflammatory diseases, auto-immune disorders, malignancies, infectious diseases and sepsis." (PMID 29641433, 2018). "Moreover, sepsis-related anti-inflammatory cytokines primarily include IL-4, IL-10, and IL-37." (PMID 40718494, 2025). "The expression of IL-37 in patients with sepsis is significantly upregulated, which could hinder the proliferation and release of pro-inflammatory cytokines and is closely related to the severity of sepsis-induced immunosuppression." (PMID 36209190, 2022). "Thus, IL-37-activated CD4+CD25+ Tregs might be advantageous to control the early inflammatory response in sepsis in vivo." (PMID 27941849, 2016). "Previous studies had identified several biomarkers such as oncostatin M (OSM), apoptosis inhibitor of the macrophage (AIM/CD5L), interleukin-26 (IL-26), interleukin-17D (IL-17D), interleukin-37 (IL-37), and growth differentiation factor-15 (GDF-15) as potential predictors of sepsis prognosis." (PMID 38318247, 2024). "Notably, Study have shown that IL-37 could significantly downregulate the expression of HLA-DR and CD86 in septic mice, inhibiting antigen presentation and indicating an immunosuppressive effect in sepsis." (PMID 40364841, 2025).
cervical cancer (12 papers, 2016 to 2025). A primary or metastatic malignant neoplasm involving the cervix. "This phenomenon may be associated with HPV infection, which might suggest that IL-37 may exert a higher anti-cancer efficiency in HPV (+) compared to that in HPV (–) cervical cancer cells." (PMID 37928545, 2023). "IL-37 was reported to promote the apoptosis of cervical carcinoma HeLa and C33A cells via up-regulating the expression of Bim." (PMID 37928545, 2023). "IL-37 has also been shown to inhibit the growth of tumor cells in renal cell carcinoma, cervical cancer, and oral squamous cell carcinoma, but all experiments were performed in vitro." (PMID 29805973, 2018). "IL-37 has been shown to suppress cell proliferation and invasion of human cervical cancer (CC) and Renal cell carcinoma (Rcc) through inhibiting STAT3 signaling." (PMID 27835881, 2016). "Recent study by Wang found that IL-37 suppressed cell proliferation and invasion of human cervical cancer (CC) through inhibiting STAT3 signaling." (PMID 26791086, 2016). "Runt related transcription factor 2 (RUNX2) can activate genes provoking tumorigenesis and metastasis, the overexpression of IL-37 in human cervical cancer cells was validated to negatively regulate their invasion by inhibiting RUNX2 at both mRNA and protein levels." (PMID 37928545, 2023). "It is already verified that IL-37 could limit excessive inflammation in this study and several published articles have revealed that IL-37 could influence apoptosis in cervical cancer and renal carcinoma." (PMID 32733162, 2020). "IL-37 also showed inhibitory effect on tumor cells in renal cell carcinoma and cervical cancer." (PMID 29805973, 2018). "In addition, IL-37 has been shown to suppress cell proliferation and invasion of human cervical cancer (CC) and Renal cell carcinoma (Rcc) through inhibiting signal transducer and activator of transcription 3 (STAT3) signaling." (PMID 27835881, 2016). "Since cervical cancer is related to human papillomavirus (HPV) infection and the chronic inflammation of the body, and chronic inflammation is closed connected with tumorigenesis, IL-37 may play diverse role in different tumors." (PMID 26791086, 2016).